LAIR1 (leukocyte associated immunoglobulin like receptor 1)
Diseases named in the same sentence as LAIR1 in open-access papers (continued):
Sharing a sentence is not in itself a finding about the gene and the disease.
celiac disease (1 paper, 2025). An autoimmune genetic disorder with an unknown pattern of inheritance that primarily affects the digestive tract. "In celiac disease, LAIR1 expression ranged from low (1+, 1/16, 6.3%), intermediate (2+, 8/16, 50%), and high (3+, 7/16, 43.8%)." (PMID 41153806, 2025). "This study analyzed the phenotype of intraepithelial lymphocytes (IELs) and the lamina propria in the small intestine, including LAIR1, and confirmed LAIR1 expression in celiac disease." (PMID 41153806, 2025). "The protein expression of LAIR1 using immunohistochemistry was evaluated in the celiac disease biopsies." (PMID 41153806, 2025). "In comparison to the small intestine control, LAIR1 lamina propria infiltration in celiac disease was higher." (PMID 41153806, 2025). "In our study, we analyzed several immuno-oncology markers in a small intestine control and, later, LAIR1 expression in celiac disease." (PMID 41153806, 2025). "A suitable independent series of celiac disease was used to validate the findings of LAIR1 at the gene expression level." (PMID 41153806, 2025). "This study aimed to analyze the phenotype of intraepithelial lymphocytes (IELs) and the lamina propria in the small intestine, including LAIR1, and to confirm the expression of LAIR1 in celiac disease." (PMID 41153806, 2025). "Images of LAIR1 protein expression analyzed by immunohistochemistry in celiac disease, small intestine control, and reactive tonsils were used as input data in a ResNet18 model." (PMID 41153806, 2025). "This study used several immuno-oncology and immune-phenotype markers to characterize the intraepithelial lymphocytes and the lamina propria of a small intestine control and to confirm the expression of LAIR1 in celiac disease." (PMID 41153806, 2025). "In celiac disease, both IELs and lamina propria cells were positive for LAIR1." (PMID 41153806, 2025). "The LAIR1 marker is relevant in intestinal mucosa immunology and celiac disease." (PMID 41153806, 2025). "In celiac disease, both IELs and many lamina propria cells were LAIR1-positive." (PMID 41153806, 2025). "Therefore, celiac disease was characterized by higher LAIR1 expression (p = 0.004)." (PMID 41153806, 2025).
chorioamnionitis (1 paper, 2013). A morphologic finding indicating inflammation of the fetal sac membranes. "The placenta with signs of severe chorioamnionitis showed infrequent positive LAIR-1 staining of cells in the chorionic plate, stromal cells in Wharton’s jelly of the umbilical cord, and the maternal side of the chorionic membranes." (PMID 24386309, 2013). "The two placentas without or with mild signs of histological chorioamnionitis were LAIR-1 negative." (PMID 24386309, 2013).
colon cancer (1 paper, 2023). "This was confirmed by reduced tumour growth and increased immune activation in a mouse model of breast and colon cancer, in case LAIR-1, TGFβR2 and PD-1/PD-L1 inhibitors were administered simultaneously, as compared to separately." (PMID 37373151, 2023).
diffuse large B-cell lymphoma (1 paper, 2025). "High LAIR1 expression in diffuse large B cell lymphoma is associated with a poor outcome." (PMID 40563506, 2025).
epilepsy (1 paper, 2018). A brain disorder characterized by episodes of abnormally increased neuronal discharge resulting in transient episodes of sensory or motor neurological dysfunction, or psychic dysfunction. "Strikingly, the increased expression of LAIR-1 in patients with epilepsy was strongly diminished after 6 and 12 months of VPA treatment, and this observation could be correlated with decreased brain seizure activity." (PMID 29958461, 2018). "Based on these findings, it is plausible to hypothesize that overexpressed LAIR-1 could inhibit the activity of C1q, consequently leading to the generation of seizures in epilepsy." (PMID 29958461, 2018). "Since the LAIR-1 promoter contains a CRE sequence, it is possible that CREB may increase the transcription of LAIR-1, generating a transcriptional regulatory loop to establish a CREB-driven transcriptional program that conceivably may trigger epilepsy." (PMID 29958461, 2018). "CREB up-regulates genes related to epilepsy; here, we suggest that LAIR1 could activate CREB, and together, they trigger epilepsy." (PMID 29958461, 2018).
inflammatory bowel disease (1 paper, 2024). A spectrum of small and large bowel inflammatory diseases of unknown etiology. "However, to the best of our knowledge, LAIR1 has not been described in other inflammatory bowel diseases." (PMID 39766129, 2024).
influenza infection (1 paper, 2022). "To observe the correlation of CRP with the local immune response of lung in mice to influenza infection, we quantified the relative expression levels of 6 immune checkpoint mRNAs in lung tissues of mice, including GITR, BTLA, TIM-3, PD-1, CTLA-4, and LAIR-1." (PMID 36275680, 2022).
Insulin resistance (1 paper, 2022). Increased resistance towards insulin, that is, diminished effectiveness of insulin in reducing blood glucose levels. "The LAIR-1 expression on Tc is associated with insulin resistance and inflammation in the context of HCC prognosis HCV G4-related, confirming the LAIR-1 resistance component." (PMID 36293412, 2022). "LAIR-1 MFI on Tc was positively correlated with insulin resistance and GLR." (PMID 36293412, 2022).
kidney cancer (1 paper, 2023). Primary or metastatic malignant neoplasm involving the kidney. "Patients with high LAIR‐1 expression had a worse clinical prognosis for kidney cancer and other cancers." (PMID 35702880, 2023). "In the kidney cancer group, the proportions of complete response (CR)/partial response (PR), and stable disease (SD)/progressive disease (PD) were 18.00 and 82.00% in the low LAIR‐1 expression group and 0.00 and 100.00% in the high LAIR‐1 expression group, correspondingly (p < 0.05)." (PMID 35702880, 2023).
lung adenocarcinoma (1 paper, 2023). A carcinoma that arises from the lung and is characterized by the presence of malignant glandular epithelial cells. "Furthermore, LAIR-1 expression in the tumor compartment was significantly higher in patients with lung adenocarcinoma (LUAD) than those with lung squamous cell carcinoma subtype (**, P = 0.003)." (PMID 36960400, 2023).
meningioma (1 paper, 2025). A generally slow growing tumor attached to the dura mater. "In accordance with higher infiltrations of immune and stromal cells and higher expression of classic immune checkpoints: CD86, PDCD1, and LAIR1, cluster 1 meningiomas might be more sensitive to immunotherapy." (PMID 41050085, 2025).
meningitis (1 paper, 2023). A disorder characterized by acute inflammation of the meninges of the brain and/or spinal cord. "C9 ADIA, LAIR1, and ADIB, all of which are associated with complement and coagulation cascades, were profoundly overexpressed in the CSF samples of patients with HEV-positive meningitis." (PMID 37153144, 2023).
myeloid neoplasm (1 paper, 2025). Proliferation of myeloid cells originating from a primitive stem cell. "Of note, one clinical trial targeting LAIR1 is listed on the website of clinicaltrials.gov (last accessed on 31 July 2025): A Safety, Tolerability and Efficacy Study of NC525 in Subjects With Advanced Myeloid Neoplasms (Id." (PMID 41153806, 2025).
pancreatic cancer (1 paper, 2025). "Combining anti-PD-1 antibodies with LAIR-1 inhibitors significantly improves treatment outcomes, as LAIR-1 blockade enhances CD4+ and CD8+ T-cell infiltration, potentiating anti-PD-L1 therapy in humanized xenograft models of colon and pancreatic cancer." (PMID 40721833, 2025).
pneumonia (1 paper, 2022). An acute, acute and chronic, or chronic inflammation focally or diffusely affecting the lung parenchyma, caused by an infection in one or both of the lungs (by bacteria, viruses, fungi, or mycoplasma.). "RNA-seq confirmed significant induction of LAIR-1 and LILRB4 dominantly in “DAD2” followed by “pneumonia”." (PMID 35992303, 2022).
sarcoma (1 paper, 2023). A usually aggressive malignant neoplasm of the soft tissue or bone. "Our results consistently showed that JBT19 human sarcoma cells stably express PD-L1, can in vivo produce high-content collagen tumors, and ex vivo be used to produce LAIR-1+ JBT19-reactive lymphocytes." (PMID 37925511, 2023).
Thrombocytosis (1 paper, 2019). Increased numbers of platelets in the peripheral blood. "Mice lacking LAIR-1 show a defect in MKs, harbor a mild thrombocytosis and their platelets are surprisingly hyper-responsive, although LAIR-1 itself is undetectable in platelets." (PMID 31398205, 2019).
Thyroid adenoma (1 paper, 2025). The presence of a adenoma of the thyroid gland. "EPOR has four fusion partners: IGH, κ (IGK), leukocyte-associated immunoglobulin-like receptor 1 (LAIR1), and thyroid adenoma-associated gene (THADA)." (PMID 39941315, 2025).
ulcerative colitis (1 paper, 2024). An inflammatory bowel disease involving the mucosal surface of the large intestine and rectum. "The CNNs also differentiated between steroid-requiring and mesalazine-responsive ulcerative colitis based on H&E, LAIR1, and TOX2 staining." (PMID 39766129, 2024). "Therefore, LAIR1 is a promising immuno-oncology marker in ulcerative colitis." (PMID 39766129, 2024). "LAIR1 and TOX2 have emerged as two promising immuno-oncology markers for ulcerative colitis." (PMID 39766129, 2024). "Finally, LAIR1 and TOX2 expressions were analyzed in the ulcerative colitis cases." (PMID 39766129, 2024). "In our study, LAIR1 was expressed by cells of the immune microenvironment, and the CNN managed to classify between steroid-requiring (SR) and nonsteroid requiring (non-SR) ulcerative colitis." (PMID 39766129, 2024).
tumor (87 papers, 2013 to 2026). "We sought to establish a correlation between the levels of CNOT7 and LAIR-1 in the blood, clinically assessing their association with tumor-node-metastasis TNM staging." (PMID 40806280, 2025). "In summary, this study elucidates the underlying mechanism of LAIR1 in tumor immunosuppression and presents a strategic approach to targeting LAIR1 through antibody blockade or signaling-deliverable CAR T cells." (PMID 40591413, 2025). "It should be noted that the analysis of gene signatures from human samples of mesothelioma identified monocyte-derived tumor-associated macrophages with a high expression of some genes, including LAIR1, in addition to TREM2, STAB1, MARCO, and GPNMB." (PMID 40563506, 2025). "Recent studies have evaluated the biological role of LAIR1 in solid tumors, and more studies are proposed to explore and define the precise mechanisms underlying the functions of LAIR-1 in tumor immunology and biology." (PMID 40591413, 2025). "LAIR1 has been detected in cervical carcinomas (CCs) in IHC assays and its expression was associated with tumor size, pathological differentiation, T histological classification, clinical stage, and the involvement of regional lymph nodes." (PMID 40563506, 2025). "This consolidation of collagen protects tumor cells by binding to soluble leukocyte-associated Ig-like receptor-1 (LAIR-1) expressing NK cells." (PMID 39511139, 2024). "Here, we studied the impact of LAIR-1 deficiency in murine tumour models and explored the mechanism behind NC410 treatment as monotherapy and in combination with known checkpoint blockers." (PMID 38236251, 2024). "Collagen is the main ECM constituent and we have previously shown that blocking the interaction of collagen with leukocyte-associated immunoglobulin-like receptor-1 (LAIR-1) results in tumour control in humanized mouse models." (PMID 38236251, 2024). "Upon engagement with tumor collagen, human LAIR-1 associates with SHP-1 and SHP-2 and proceeds to dephosphorylate VAV1, thereby dampening NK activation." (PMID 39511139, 2024). "In contrast, high LAIR-1 tumor expression in LUAD subtype was significantly associated with reduced OS (HR = 2.4; *, P = 0.022)." (PMID 36960400, 2023). "Our results indicated that high tumor LAIR-1 expression in patients with LUAD is negatively associated with OS (overall survival, HR = 2.4; *, P = 0.02) highlighting its prognostic value in LUAD but not in other subtypes." (PMID 36960400, 2023). "The mechanism of resistance resulted from increased collagen levels in the tumor extracellular matrix which induced T cell exhaustion via the leukocyte-associated immunoglobulin-like receptor 1 (LAIR1)." (PMID 38002335, 2023). "The association of LAIR-1 with poor outcome in immunotherapy-treated patients merits further studies to explore its role in tumor biology." (PMID 36960400, 2023). "Stimulating the function of LAIR-1 to inhibit tumor growth, which causes T cells to fail, results in a decreased immune response." (PMID 37511932, 2023). "We additionally assessed the cell densities of LAIR-1+/CK+ tumor cells with regards to their association with OS as compared with LAIR-1 QIF scores in tumor compartment by AQUA." (PMID 36960400, 2023). "Our in vitro co-culture studies identify a regulatory loop whereby tumor-associated collagen recognition by CD18 (ITGβ2) on leukocytes upregulates LAIR1 expression, which subsequently promotes CD8+ T cell exhaustion through SHP-1 signaling." (PMID 32908154, 2020). "In hepatocellular carcinoma, LAIR-1 expression is positively associated with tumour grade, stage, and worse overall survival." (PMID 33396670, 2020). "Here we found that high LAIR-1 expression was associated with a more advanced OS tumor stage (P = 0.006)." (PMID 32563267, 2020). "The expression of LAIR-1 in tumour cells and its association with immune cell function supports a role for LAIR-1 in tumour biology and thus requires further studies." (PMID 33396670, 2020).
tumor (continued). "Collagens act as functional ligands for the immune inhibitory receptor, Leukocyte Associated Ig-like Receptor-1 (LAIR-1), and tumor-expressed collagens can trigger immune inhibitory signaling via LAIR-1." (PMID 29970158, 2018). "Human leukocyte-associated immunoglobulin-like receptor-1 (LAIR-1), an immunoinhibitory receptor, is expressed on most types of hematopoietic cells and some tumor cells." (PMID 29915163, 2018). "It should be clarified whether the high LAIR1 expression associated with advanced tumor stages is due to the presence of infiltrating LAIR1+ immune cells or LAIR1+ cancer cells." (PMID 40563506, 2025). "Leukocyte-associated immunoglobulin-like receptor 1 (LAIR-1) is highly expressed in tumor cells." (PMID 37511932, 2023). "We showed by RNA analysis that high expression of total collagens, LAIR-1, and combined high total collagen and high LAIR-1 are associated with a worse prognosis in multiple tumor types, supporting the notion of disrupting LAIR-1-collagen interactions as a novel immunotherapeutic strategy." (PMID 34121658, 2021). "High LAIR-1 mRNA expression was associated with higher histological tumour grade, high NPI, Basal and human epidermal growth factor receptor 2 (HER2) enriched PAM50 subtypes and hormone receptor oestrogen receptor (ER) and progesterone receptor (PgR)) negativity (all p < 0.001)." (PMID 33396670, 2020). "According to these observations, we investigated the association between LAIR-1 overexpression and human OS tumor growth and examined whether LAIR-1 overexpression exhibits a compensatory effect to help overcome OS progression." (PMID 32563267, 2020). "Although previous studies have evaluated the biological role of LAIR in solid tumors, the precise mechanisms underlying the functions of LAIR-1 as a regulator of tumor biological functions remain unclear." (PMID 32563267, 2020). "We observed a significant positive association between collagens with high expression of LAIR-1 mRNA, implying that high expression of collagens by tumour cells may enable these cells to suppress anti-tumour responses via the LAIR-1 immuno-inhibitor." (PMID 33396670, 2020). "The intervention using anti-Lair1 antibody resulted in multiple actions, including repolarization of M2-like MΦ to M1 MΦ for an antitumor effect, enhancement of tumor–T cell interaction for cytolytic killing, and reduction of tumor-associated collagen deposition to normalize the TME." (PMID 40591413, 2025). "Moreover, tumours overexpressing collagens are associated with poor patient survival and this may be related to collagen-mediated immune cell modulation via LAIR-1." (PMID 33396670, 2020). "Several inhibitory markers, including CD276, HAVCR2, CTLA4, PDCD1LG2, LAIR1, and ADORA2A, were significantly upregulated in the high-risk group (p < 0.05), suggesting an immunosuppressive tumor microenvironment." (PMID 40963600, 2025). "In contrast, Lair1–/– tumors showed significantly reduced collagen deposition and clearly exposed tumor nuclei, more closely resembling normal brain tissue." (PMID 40591413, 2025). "Second, their results reinforce other reports that blocking LAIR1 signaling reduces tumor growth, increases survival, and enhances antitumor immune responses." (PMID 40829176, 2025). "Surprisingly, in vitro treatment of PD-1–resistant murine GBM cells with FXIII-A alone also led to increased collagen IV staining similar to that seen in untreated Lair1+/+ GBM tumor–bearing mice." (PMID 40829176, 2025). "The effect of the anti-Lair1 antibody on NAS T cells followed a similar trend but to a much lesser extent in terms of T cell–tumor interactions and tumor inhibition, likely due to the lack of antigen specificity." (PMID 40591413, 2025). "The peripheral effect of anti-Lair1 antibody on enhancing tumor immunity proves crucial for the observed in vivo antitumor response." (PMID 40591413, 2025).